KLRD1 (killer cell lectin like receptor D1)
Description:
Immune receptor involved in self-nonself discrimination. In complex with KLRC1 or KLRC2 on cytotoxic and regulatory lymphocyte subsets, recognizes non-classical major histocompatibility (MHC) class Ib molecule HLA-E loaded with self-peptides derived from the signal sequence of classical MHC class Ia and non-classical MHC class Ib molecules. Enables cytotoxic cells to monitor the expression of MHC class I molecules in healthy cells and to tolerate self. Primarily functions as a ligand binding subunit as it lacks the capacity to signal. KLRD1-KLRC1 acts as an immune inhibitory receptor. Key inhibitory receptor on natural killer (NK) cells that regulates their activation and effector functions. Dominantly counteracts T cell receptor signaling on a subset of memory/effector CD8-positive T cells as part of an antigen-driven response to avoid autoimmunity. On intraepithelial CD8-positive gamma-delta regulatory T cells triggers TGFB1 secretion, which in turn limits the cytotoxic programming of intraepithelial CD8-positive alpha-beta T cells, distinguishing harmless from pathogenic antigens. In HLA-E-rich tumor microenvironment, acts as an immune inhibitory checkpoint and may contribute to progressive loss of effector functions of NK cells and tumor-specific T cells, a state known as cell exhaustion. Upon HLA-E-peptide binding, transmits intracellular signals through KLRC1 immunoreceptor tyrosine-based inhibition motifs (ITIMs) by recruiting INPP5D/SHIP-1 and INPPL1/SHIP-2 tyrosine phosphatases to ITIMs, and ultimately opposing signals transmitted by activating receptors through dephosphorylation of proximal signaling molecules. KLRD1-KLRC2 acts as an immune activating receptor. On cytotoxic lymphocyte subsets recognizes HLA-E loaded with signal sequence-derived peptides from non-classical MHC class Ib HLA-G molecules, likely playing a role in the generation and effector functions of adaptive NK cells and in maternal-fetal tolerance during pregnancy. Regulates the effector functions of terminally differentiated cytotoxic lymphocyte subsets, and in particular may play a role in adaptive NK cell response to viral infection. Upon HLA-E-peptide binding, transmits intracellular signals via the adapter protein TYROBP/DAP12, triggering the phosphorylation of proximal signaling molecules and cell activation. (Microbial infection) Viruses like human cytomegalovirus have evolved an escape mechanism whereby virus-induced down-regulation of host MHC class I molecules is coupled to the binding of viral peptides to HLA-E, restoring HLA-E expression and inducing HLA-E-dependent NK cell immune tolerance to infected cells. Recognizes HLA-E in complex with human cytomegalovirus UL40-derived peptide (VMAPRTLIL) and inhibits NK cell cytotoxicity. (Microbial infection) May recognize HLA-E in complex with HIV-1 gag/Capsid protein p24-derived peptide (AISPRTLNA) on infected cells and may inhibit NK cell cytotoxicity, a mechanism that allows HIV-1 to escape immune recognition. (Microbial infection) Upon SARS-CoV-2 infection, may contribute to functional exhaustion of cytotoxic NK cells and CD8-positive T cells. On NK cells, may recognize HLA-E in complex with SARS-CoV-2 S/Spike protein S1-derived peptide (LQPRTFLL) expressed on the surface of lung epithelial cells, inducing NK cell exhaustion and dampening antiviral immune surveillance.
Synonyms: CD94
Tractability: Antibody: UniProt places it where antibodies can reach, with high confidence; its Gene Ontology location is reachable by antibodies, with high confidence; UniProt predicts a signal peptide or a membrane-spanning region.
Gene: Protein-coding gene on chromosome 12 (10,226,058 to 10,329,608, forward strand). Ensembl gene ENSG00000134539.
Subcellular location: Cell membrane
Pathways (Reactome):
Immune System: DAP12 interactions; DAP12 signaling; Immunoregulatory interactions between a Lymphoid and a non-Lymphoid cell
Gene Ontology:
Molecular function: HLA-A specific activating MHC class I receptor activity; HLA-E specific inhibitory MHC class Ib receptor activity; MHC class I protein complex binding; MHC class Ib protein binding, via antigen binding groove; protein antigen binding; protein binding; transmembrane signaling receptor activity
Biological process: natural killer cell mediated immunity; negative regulation of natural killer cell mediated cytotoxicity; negative regulation of T cell mediated cytotoxicity; positive regulation of natural killer cell mediated cytotoxicity; stimulatory C-type lectin receptor signaling pathway; cell surface receptor signaling pathway; regulation of natural killer cell activation
Cellular component: plasma membrane; receptor complex; cell surface; external side of plasma membrane
Genetic constraint (gnomAD): Loss-of-function variants: 8 observed, 10.85 expected, observed/expected ratio (o/e) 0.74, 90% interval 0.43 to 1.33. The upper end of that interval is the gene's LOEUF score, 1.33, which puts it in group 5 of 6, group 1 being the genes least tolerant of losing a copy. Missense variants: 84 observed, 87.46 expected, observed/expected ratio (o/e) 0.96, 90% interval 0.8 to 1.15. Synonymous variants: 19 observed, 29 expected, observed/expected ratio (o/e) 0.66, 90% interval 0.46 to 0.96.
Homologues: Orthologues: chimpanzee KLRD1 (99% identical), macaque KLRD1 (92% identical), pig KLRD1 (62% identical), rabbit KLRD1 (60% identical), dog KLRD1 (59% identical), guinea pig KLRD1 (57% identical), mouse Klrd1 (54% identical), rat Klrd1 (54% identical), Drosophila melanogaster rgn (23% identical), zebrafish si:ch211-170d8.8 (22% identical), zebrafish si:dkey-26c10.5 (21% identical), zebrafish si:ch211-193e13.5 (20% identical), and 2 more. Paralogues in human: KLRC1 (30% identical), CLEC12B (29% identical), CLEC7A (29% identical), KLRC2 (28% identical), OLR1 (28% identical), KLRC3 (27% identical), CLEC12A (26% identical), CLEC1A (26% identical), KLRK1 (25% identical), CLEC9A (25% identical), KLRB1 (24% identical), CLEC1B (23% identical), and 11 more.
Diseases named in the same sentence as KLRD1 in open-access papers:
KLRD1 is named in the same sentence as 113 diseases in open-access papers, as found by Europe PMC text mining. Sharing a sentence is not in itself a finding about the gene and the disease. The quoted sentences say what the papers report.
viral infection (29 papers, 2010 to 2025). "A negative correlation between expression of KLRD1 and the severity of viral infection, including SARS-CoV-2, further emphasizes that KLRD1-expressing NK cells may play a protective role following infection, irrespective of the infecting virus." (PMID 33765435, 2021).
COVID-19 (11 papers, 2021 to 2025). A disease caused by infection with severe acute respiratory syndrome coronavirus 2. "Therefore, whether the postvaccination upregulation of KLRD1 expression can confer protection by promoting the expressions of GZMB and PRF1, and whether KLRD1 expression is related to COVID-19 susceptibility needs to be clarified." (PMID 37654490, 2023).
melanoma (11 papers, 2016 to 2025). A malignant, usually aggressive tumor composed of atypical, neoplastic melanocytes. "Copy number loss in KLRD1 was seen in melanoma and associated with lower T cell infiltrate and poor prognosis which may have relevance to the patients here." (PMID 35652109, 2022).
influenza (10 papers, 2011 to 2023). An acute viral infection of the respiratory tract, occurring in isolated cases, in epidemics, or in pandemics; it is caused by serologically different strains of viruses (influenzaviruses) designated A, B, and C, has a 3-day incubation period, and usually lasts for 3 to 10 days. "KLRD1 expression in circulating NK cells at baseline negatively correlated with influenza susceptibility and symptom severity." (PMID 37654490, 2023). "What’s more, natural killer (NK) cells were significantly lower in symptomatic shedders before influenza exposure at baseline level and KLRD1 as a key predictor used to predict influenza susceptibility." (PMID 36713410, 2022). "In conclusion, we identified KLRD1-expressing NK cells as a novel biomarker for influenza susceptibility." (PMID 29898768, 2018). "Interestingly, the expression level of KLRD1 was recently reported as a promising biomarker for predicting human susceptibility to influenza." (PMID 36341362, 2022). "We identified KLRD1-expressing NK cells as a potential biomarker for influenza susceptibility." (PMID 29898768, 2018). "In the HRV challenge study (GSE11348), KLRD1 expression at 8 h post-infection was significantly inversely correlated with symptom severity (r = − 0.6, P = 0.031) similar to influenza challenge studies." (PMID 29898768, 2018). "We observed that expression of KLRD1 decreased in symptomatic shedders 48 h post-influenza inoculation." (PMID 29898768, 2018). "We also observed that KLRD1 expression decreased in the blood during the first 48 h of influenza infection." (PMID 29898768, 2018). "KLRD1 expression in the blood at baseline negatively correlated with influenza infection symptom severity." (PMID 29898768, 2018). "As KLRD1 expression in the blood reflects NK cell numbers, this suggests that KLRD1-expressing NK cells are protective against influenza infection in humans." (PMID 29898768, 2018). "have analyzed the baseline immunization spectrum of volunteers before vaccination against influenza and found that, after vaccination, the expression levels of KLRD1 in the peripheral blood of symptomatic volunteers was lower than that of asymptomatic patients." (PMID 35059324, 2021). "This suggests that KLRD1-expressing NK cells may be important for controlling influenza symptom severity." (PMID 29898768, 2018). "Our results imply that an early response by KLRD1-expressing NK cells may reduce symptom severity and possibly prevent influenza infection entirely." (PMID 29898768, 2018). "Our results support a model where an early response by KLRD1-expressing NK cells may control influenza infection." (PMID 29898768, 2018). "We also investigated the temporal expression of KLRD1 during influenza infection." (PMID 29898768, 2018). "Our results support a model where a rapid response by KLRD1-expressing NK cells can lessen severity of or may prevent influenza infection." (PMID 29898768, 2018). "The role of KLRD1 (CD94) in influenza susceptibility cannot be fully understood without considering which NKG2 family members are involved." (PMID 29898768, 2018). "Therefore, we sought to examine expression of KLRD1 in nasal epithelium during acute influenza infection." (PMID 29898768, 2018). "Our results suggest that KLRD1 expressing NK cells may be protective against influenza." (PMID 29898768, 2018). "The high expression levels of KLRD1 may help effector CD8+ T cells to survive and thus protect against influenza." (PMID 35059324, 2021). "However, it is also possible that KLRC3 expression in the blood simply reflects the number of NK cells present and that KLRD1-expressing NK cells are protective against influenza using a mechanism independent of NKG2E or NKG2H signaling." (PMID 29898768, 2018).
influenza (continued). "Based on our previous report describing a robust common host immune response to acute respiratory viral infection including influenza, HRV, and RSV, we hypothesized that KLRD1 expression will change in the nasal epithelium of individuals infected with HRV or RSV." (PMID 29898768, 2018).
breast carcinoma (6 papers, 2020 to 2023). "To further explore the identified CD226, KLRD1, and KLRC4-KLRK1 genes with prognostic value, we analyzed the expression of these genes and their association with OS in different breast cancer stages or subtypes." (PMID 33549054, 2021).
colon carcinoma (4 papers, 2015 to 2022). "ILC1s expressed inhibitory receptors and underwent inhibitory functional conversion in late stage colon cancers while ILC1s in early-stage tumors expressed high levels of activating receptors (KLRD1, NCR1, KLRC2, KLRB1C) while late-stage colon cancers expressed inhibitory markers (KLRE1, KLRA7)." (PMID 36189323, 2022).
endometriosis (4 papers, 2019 to 2023). The growth of functional endometrial tissue in anatomic sites outside the uterine body. "The analysis of NK cells from peripheral blood and peritoneal fluid from women with endometriosis did not reveal any change of expression of CD94 (KLRD1)." (PMID 31540116, 2019).
Sepsis (4 papers, 2016 to 2026). Sepsis is defined as life-threatening organ dysfunction caused by a dysregulated host response to infection. "Principal component analysis of GZMA, GZMB, CD8A, CD8B, KLRD1, PRF1 and LAG3 gene expression revealed 81% explained variance for the first principal component considering HIV negative and HIV positive sepsis patients." (PMID 26871709, 2016).
acute GVHD (3 papers, 2016 to 2024). "We found weak genetic associations between polymorphisms in the CD226, CD244, FCGR3A, KLRD1, NCR3, and PVRIG genes, and the risks for relapse, acute GVHD, and chronic GVHD in the HSCT discovery cohort but not in the replication cohort." (PMID 39506082, 2024).
bladder cancer (3 papers, 2024 to 2025). "Single-cell analysis revealed that KLRD1 is predominantly expressed in NK cells and CD8Tex cells across various cancers, particularly in bladder cancer (BLCA), HNSC, KIRC, non-small cell lung cancer (NSCLC), pancreatic cancer (PAAD), peripheral blood mononuclear cells (PBMC), and SKCM." (PMID 39781341, 2025). "We developed a Risk Score model that was related to the overall survival of bladder cancer patients based on doxorubicin-target HRGs: ACTG2, MYC, PDGFRB, DHRS2, and KLRD1." (PMID 38806990, 2025).
malaria (3 papers, 2020 to 2023). Malaria is a serious and sometimes fatal disease caused by a parasite that commonly infects a certain type of mosquito which feeds on humans. "Klrd1, Klrc1, and Klrc3 reveal similar expression courses in response to malaria and to vaccination." (PMID 33202767, 2020). "Moreover, similar time course of expressions are detected, both by qRT-PCR and microarrays, for Klrg1 and Klrd1 as well as Klrb1f and Clec2i in both vaccinated and non-vaccinated mice in response to malaria and vaccination." (PMID 33202767, 2020).
psoriasis (3 papers, 2011 to 2025). An autoimmune condition characterized by red, well-delineated plaques with silvery scales that are usually on the extensor surfaces and scalp. "The seven genes span established–emerging–novel tiers: PRF1 and KLRC1/KLRD1 are established in psoriasis immunity; SLFN5 is a recently reported systemic inflammatory marker; BIN2/CXXC5/CAPN12 lack prior links, suggesting novelty." (PMID 41328434, 2025). "Additional Mendelian randomization analysis pinpointed seven marker genes linked to psoriasis: BIN2, CAPN12, CXXC5, KLRC1, KLRD1, PRF1, and SLFN5." (PMID 41328434, 2025). "By integrating single-cell RNA sequencing with MR analysis, we identified seven psoriasis-related genes (BIN2, CAPN12, CXXC5, KLRC1, KLRD1, PRF1, and SLFN5) that are highly expressed in CD4+ T cells." (PMID 41328434, 2025). "Because of such prior evidence, KLRC1 and KLRD1 are not novel to psoriasis: they have been studied and recognized as part of the disease’s immune dysregulation." (PMID 41328434, 2025). "KLRC1, KLRD1, PRF1, BIN2, and SLFN5 showed enrichment concentrated in immune-inflammatory modules—including IL-17 signaling, the TNF/NF-κB axis, and innate immune sensor pathways (NOD-, RIG-I-, and Toll-like receptors)—consistent with psoriasis-relevant Th17/innate activation." (PMID 41328434, 2025).
rheumatoid arthritis (3 papers, 2011 to 2024). A chronic, systemic autoimmune disorder characterized by inflammation in the synovial membranes and articular surfaces. "A study of rheumatoid arthritis single-cell RNA sequencing data demonstrated that five genes, KLRG1, CRTAM, SLAMF7, PTPN2, and KLRD1, were downregulated in activated and effector T cells isolated from synovial fluids." (PMID 38254179, 2024).
sarcoma (3 papers, 2020 to 2024). A usually aggressive malignant neoplasm of the soft tissue or bone. "T‐cells in the sarcoma microenvironment exhibited elevated levels of cytotoxicity (GZMB, GNLY and KLRD1), exhaustion (HAVCR2, CD38, CD160, CXCL13 and CX3CR1), and inflammation (IL33, PPARG, IL6R and SOCS3), suggesting an activated but exhausted phenotype." (PMID 39658531, 2024).
autoimmune disorders (2 papers, 2010 to 2023). "Similarly, DBA/2J mice have a spontaneously arising mutation in the Klrd1 gene that prevents expression of CD94, yet NK cells develop normally in these mice and do not cause overt autoimmunity." (PMID 21151939, 2010).
glaucoma (1 paper, 2014). Increased pressure in the eyeball due to obstruction of the outflow of aqueous humor. "To test the role of the CD94/NKG2A- Qa-1b axis in ocular immune regulation and glaucoma progression, we generated D2 mice that are sufficient in CD94 (D2 Klrd1+/+)." (PMID 24678736, 2014).
liver failure (1 paper, 2021). A liver disease characterized by the liver losing or has lost all of its function. "Several elevations signified an emergence of liver failure in the urine level of CCL3, KLRD1, MUC-16, KIRLD1, TWEAK, VEGF r2." (PMID 34608231, 2021).
trachoma (1 paper, 2021). "The mRNA expression of KLRD1 often increased in the inflammatory response, for instance, HIV infection, trachoma, and gut dysbiosis." (PMID 34271875, 2021).